ASXL3 (ASXL transcriptional regulator 3)
Description:
Putative Polycomb group (PcG) protein. PcG proteins act by forming multiprotein complexes, which are required to maintain the transcriptionally repressive state of homeotic genes throughout development. PcG proteins are not required to initiate repression, but to maintain it during later stages of development. They probably act via methylation of histones, rendering chromatin heritably changed in its expressibility (By similarity). Non-catalytic component of the PR-DUB complex, a complex that specifically mediates deubiquitination of histone H2A monoubiquitinated at 'Lys-119' (H2AK119ub1). The PR-DUB complex is an epigenetic regulator of gene expression and acts as a transcriptional coactivator, affecting genes involved in development, cell communication, signaling, cell proliferation and cell viability. ASXL1, ASXL2 and ASXL3 function redundantly in the PR-DUB complex and are essential for chromatin recruitment and transcriptional activation of associated genes (By similarity).
Synonyms: KIAA1713; BRPS
Tractability: PROTAC: ubiquitination databases record sites on it.
Gene: Protein-coding gene on chromosome 18 (33,578,219 to 33,751,195, forward strand). Ensembl gene ENSG00000141431.
Subcellular location: Nucleus
Gene Ontology:
Molecular function: chromatin binding; peroxisome proliferator activated receptor binding; DNA binding
Biological process: negative regulation of lipid biosynthetic process; animal organ morphogenesis; positive regulation of transcription by RNA polymerase II; regulation of DNA-templated transcription
Cellular component: PR-DUB complex; nucleus
Genetic constraint (gnomAD): Loss-of-function variants: 24 observed, 147.7 expected, observed/expected ratio (o/e) 0.16, 90% interval 0.12 to 0.23. The upper end of that interval is the gene's LOEUF score, 0.23, which puts it in group 1 of 6, group 1 being the genes least tolerant of losing a copy. Missense variants: 2,508 observed, 2,678.4 expected, observed/expected ratio (o/e) 0.94, 90% interval 0.9 to 0.97. Synonymous variants: 966 observed, 991.54 expected, observed/expected ratio (o/e) 0.97, 90% interval 0.92 to 1.03.
Gene-disease validity (ClinGen):
ClinGen rates the evidence that ASXL3 causes each of these diseases.
syndromic intellectual disability (autosomal dominant): Definitive. A intellectual disability that is part of a larger syndrome.
Homologues: Orthologues: chimpanzee ASXL3 (99% identical), macaque ASXL3 (97% identical), rabbit ASXL3 (88% identical), pig ASXL3 (88% identical), dog ASXL3 (88% identical), guinea pig ASXL3 (86% identical), mouse Asxl3 (82% identical), rat Asxl3 (82% identical), tropical clawed frog asxl3 (53% identical), Drosophila melanogaster Asx (12% identical). Paralogues in human: ASXL1 (20% identical), ASXL2 (20% identical).